INS (insulin)
Diseases named in the same sentence as INS in open-access papers (continued):
Sharing a sentence is not in itself a finding about the gene and the disease.
Insulin resistance (continued). "Therefore, American ginseng may improve insulin resistance by reducing lipotoxicity in muscle and liver through increasing the ability to store lipids in adipocytes, and enhance insulin sensitivity through increase of adipocyte GLUT4 expression." (PMID 30616613, 2019). "Thus, it is tempting to speculate whether adult-onset hypothalamic insulin resistance might be a functional consequence of increased hypothalamic insulin signaling during early life." (PMID 31572115, 2019). "Therefore, the development and use of drugs that could improve patients' insulin sensitivity and improve the state of insulin resistance were of great significance for the treatment of diabetes." (PMID 31072232, 2019). "In addition, the low expression levels of FOXO1 suggested it may activate insulin production and insulin resistance signaling to enhance glucose and lipid metabolism in the liver." (PMID 31456815, 2019). "Moreover, the positive effect of flavonoids on insulin-signaling pathways are supported by data observed in clinical trials, as they suggest that the intake of flavonoid-rich food may decrease insulin resistance." (PMID 31027340, 2019). "Therefore, it may be that insulin resistance is a condition affecting both peripheral and central insulin signaling pathways, and insulin resistance constitutes a potential link between metabolic and cognitive dysfunction." (PMID 31440156, 2019). "Collectively, our study revealed a new mechanism underlying SFA’s insulin-sensitizing properties and suggested that therapeutically targeting ceramide synthesis through inhibiting SPTLC3 might be an effective therapeutic for insulin resistance." (PMID 31137828, 2019). "However, the effect of insulin could be due to insulin resistance in endothelial cells which decreases eNOS activity, or to modifications on the downstream substrates of the insulin receptor." (PMID 30717220, 2019). "In addition, early-insulin sensitivity could give rise to insulin resistance later in life, as seen in offspring exposed to low protein diets in utero who tend to demonstrate insulin resistance after one year of age50,52." (PMID 31300679, 2019). "Thus, the aim of this study was to assess the suitability of replacing conventional markers used for insulin resistance and dysglycemia (FPG, the homeostasis assessment model for insulin resistance [HOMA-IR] or fasting insulin) with HbA1c in both quantitative and qualitative MetS criteria." (PMID 31805696, 2019). "A lipodystrophy-like phenotype, which is significantly associated with abnormalities in lipid storage (e.g., lower leg fat mass, impaired insulin secretion capacity, and insulin resistance) and decreased cardiorespiratory fitness, may exist in the general population." (PMID 31697720, 2019). "In addition, quantification of a number of well-characterized hepatic insulin signaling genes (Irs1, P85a, and P110b) that have been recognized to correlate with insulin resistance indicated that loss of Agrp did not prevent the changes in these genes." (PMID 30794724, 2019). "Furthermore, studies have shown that there is a direct interaction between oxidative stress and insulin resistance, and the accumulation of oxidation products may damage critical macromolecules in insulin-sensitive tissues." (PMID 31013790, 2019). "Increased consumption or supplementation of many of these nutrients, including, but not limited to fiber, unsaturated fatty acids, vitamin A, vitamin B6, and magnesium may contribute to improved insulin sensitivity, decreased insulin resistance, and the prevention of T2DM." (PMID 31514469, 2019). "Insulin potently recruits muscle microvasculature in healthy humans but fails to do so in obese humans or healthy humans receiving systemic infusion of lipid solution, which acutely raises plasma concentrations of free fatty acids (FFA) and causes metabolic insulin resistance." (PMID 30699907, 2019).
Insulin resistance (continued). "Therefore, a hypothesis came into being that mulberry leaf could ameliorate proinflammation and insulin resistance (IR) through TLRs and insulin signalling pathways." (PMID 31752797, 2019). "In order to develop a model of insulin resistance induced by PA in hepatic cells, HepG2 cells were first exposed to rising doses of PA (0, 25, 50, 100, 150 and 200 μM) for 12, 24 or 36 h followed by 100 nM insulin stimulation for 10 min and cell viability were evaluated." (PMID 31137828, 2019). "Furthermore, possible cellular mechanisms by which GRE may ameliorate lipid-induced hepatic insulin resistance were elucidated by exploring downstream signal pathways involved in insulin and AMPK-mediated pathways." (PMID 30717198, 2019). "In addition, catecholamines antagonize insulin action in target organs and thereby might trigger insulin resistance." (PMID 30959789, 2019). "Noteworthy, we set up and fully characterized an in vitro model of insulin resistance developed in cholinergic neurons, to study the underlying molecular events and assess candidate drug, like nerve growth factor (NGF), for counteracting the insulin-resistant state of BFCN." (PMID 29736736, 2019). "Our study found that administration of a vitamin-rich carbohydrate beverage (5 ml by gavage) could effectively attenuate postoperative insulin resistance, improve insulin sensitivity, and decrease the production of IL-1β and S-100β in the plasma of elderly rats after splenectomy." (PMID 31092210, 2019). "Although the mechanisms underlying the brain insulin resistance are not fully elucidated, it is speculated to result either from impaired response in neuronal insulin signaling or reduced blood-to-brain transport of insulin, or both." (PMID 30975165, 2019). "Glycated insulin is less effective in controlling glucose homeostasis and stimulating glucose uptake than non-glycated insulin, and thus glycation might contribute to the insulin resistance and glucose intolerance of type 2 diabetes (T2D)." (PMID 31652867, 2019). "Systemic insulin resistance is characterized by the inability of insulin to reduce blood glucose levels appropriately because of the impaired translocation of the GLUT4 receptor to the surface membrane of the muscle cell and leading to loss of insulin-dependent uptake of glucose." (PMID 30642126, 2019). "A high-fat diet has been widely described to induce insulin resistance in rodent models, and it has also been used to elucidate the relationship between the metabolic insult elicited by increased fatty acids supply, insulin resistance and mitochondrial function." (PMID 31130874, 2019). "Although the mechanism of how RET4 affects insulin sensitivity is not clear, RET4 may cause insulin resistance by inducing the gluconeogenic enzyme, phosphoenolpyruvate carboxykinase, in the liver and by impairing insulin signaling in muscles." (PMID 31623319, 2019). "However, the relationship of LRP5 (rs556442) polymorphism with insulin sensitivity and insulin resistance in children has not been examined as yet." (PMID 30866603, 2019). "SIRT1 may play a crucial role in reducing inflammation and oxidative stress and improving mitochondrial function, resulting in both the protection of pancreatic β cells and amelioration of insulin resistance in insulin-sensitive tissues such as skeletal muscle and adipose tissue." (PMID 30972029, 2019). "The pathogenesis associated with this increase in the prevalence of T2DM may be attributed to stress-mediated insulin resistance and/or decreased insulin sensitivity, which results in T2DM development through inflammatory response, oxidative stress, and endoplasmic reticulum." (PMID 31341475, 2019). "We also do not have nonfasting measures of insulin resistance in our cohort and therefore could not assess whether insulin levels throughout the day affect the association of SHBG and NAFLD." (PMID 32128321, 2019).
Insulin resistance (continued). "A treatment that specifically increases Tregs may be useful for the treatment of insulin resistance, and pioglitazone, a drug used to treat T2D, can increase insulin sensitivity by stimulating PPAR-γ signaling in Tregs, resulting in an increased frequency of Tregs in adipose tissue." (PMID 31297120, 2019). "In mice, obesity and the associated visceral adipose tissue inflammation result in insulin resistance, a process which appears to be mediated via increased synthesis and release of hepatic DPP-4, since eliminating hepatocyte Dpp4 expression suppresses inflammation and improves insulin sensitivity." (PMID 30828317, 2019). "Furthermore, this study will assist healthcare providers in making informed decisions relating to screening of depressed patients for insulin resistance and subsequent use of insulin sensitivity-enhancing interventions in patients with treatment-resistant depression and comorbid insulin resistance." (PMID 30803432, 2019). "The reduced sensitivity to insulin in peripheral organs and tissues such as the liver, skeletal muscle, and adipose tissue alters glucose homeostasis by a reduction in glucose uptake, leading to hyperglycaemia and, therefore, insulin resistance and type 2 diabetes." (PMID 31354915, 2019). "The severity of illness and degree of insulin resistance during an ICU stay may cause changes in nutritional delivery and other interventions (e.g., corticosteroid administration) and may produce frequent changes in insulin requirements." (PMID 31052277, 2019). "Resistin could be a link between insulin resistance and obesity; its release reduces peripheral insulin sensitivity, increases endogenous glucose production by the liver, induces insulin resistance, and stimulates proinflammatory cytokines (e.g., IL-6 and tumor necrosis factor (TNF)-α)." (PMID 31671697, 2019). "Impaired transduction of insulin signaling, being related to decreased activity of glucose transporter as a result of alterations of intracellular Ca2+ in target tissues, may lead to peripheral insulin resistance." (PMID 30959886, 2019). "However, on closer examination, the discrepant findings from the two studies were explained by differences in baseline levels of insulin action, such that DHEA improves insulin action, along with associated reductions in IL6 and TNFα, primarily in subjects who have insulin resistance at baseline." (PMID 30730811, 2019). "While insulin production is present in this form, the quantity produced may be insufficient to meet the body's needs or in some cases may be owing to the development of insulin resistance." (PMID 31687377, 2019). "Consistent to our findings, a randomized controlled trial conducted in Iran showed that daily consumption of probiotic yogurt for nine weeks maintained serum insulin levels and might help to prevent pregnant women from developing insulin resistance, compared with conventional yogurt." (PMID 31497545, 2019). "Furthermore, Bacteroidetes is known to be the major bacterium producing acetate (C2) and propionate (C3) in the intestine, which can induce glucose-stimulated insulin secretion and insulin resistance through activation of the parasympathetic nerve system and lipogenesis." (PMID 31409765, 2019). "Thus, the effects of insulin and insulin resistance on the BFCS and related cognition is of great relevance for ameliorating insulin resistance-dependent impairment of cognition observed in both neurodegenerative disorders (e.g. AD) and metabolic diseases (e.g. Type 2 Diabetes, T2D)." (PMID 29736736, 2019). "Therefore, IRS phosphorylation on these serine residues was considered as an indicator of insulin resistance that prevents the active insulin interaction with its receptors, a fact that supports the present effect of AlCl3 on heightening the hippocampal content of pSer307-IRS1." (PMID 31137621, 2019).
Insulin resistance (continued). "Despite the well-established insulin sensitivity-enhancing potential of these interventions, there has not been any previous comprehensive study or systematic review evaluating a possible link between their antidepressant effect and potential to correct insulin resistance in depressed patients." (PMID 30803432, 2019). "High-fat diets, in particular diets rich in SFAs, may promote insulin resistance through several mechanisms, such as insulin signaling interfering, the promotion of inflammation through tumor necrosis factor alpha (TNF-α) production, and increased oxidative stress." (PMID 30717458, 2019). "The “expandability hypothesis” suggests that fat accumulation in organs outside of the adipose tissue leads to cell death, inflammation, and insulin resistance providing one explanation for obesity-driven insulin resistance as well as insulin-sensitive obesity." (PMID 30409703, 2019). "Thus, a better understanding of mechanisms that lead to SKM insulin resistance may lead to the development of novel antidiabetic drugs that act by improving SKM insulin sensitivity." (PMID 31622341, 2019). "In addition, NOCTURNIN seems to be involved in the regulation of glucose homeostasis and insulin sensitivity and may promote insulin resistance." (PMID 31467910, 2019). "The last category include indirect markers which do not use insulin or glucose but newer markers which the literature search has identified to be associated with insulin resistance like ferritin, insulin growth factor binding protein-1, adiponectin, resistin, and some other chemical compounds." (PMID 31223343, 2019). "Thus, a possibility exists that alternate phosphorylation and O-GlcNAcylation of insulin signaling intermediates, including PHB, at common sites or adjacent sites may cause sex differences in insulin resistance and consequently metabolic dysregulation." (PMID 31118075, 2019). "Furthermore, lactate induces insulin resistance and inhibits insulin action." (PMID 32128099, 2019). "In addition, plenty of researches have demonstrated that E2 administration could ameliorate insulin resistance and enhance insulin sensitivity." (PMID 31849684, 2019). "However, in a dose response study in obese individuals with insulin resistance, a beverage containing 40 g of freeze-dried strawberry powder significantly reduced the post-meal demand for insulin compared to a control beverage devoid of polyphenols, but matched for fiber." (PMID 31013914, 2019). "Aerobic exercise has been shown to improve insulin signaling and glucose metabolism and promoting the production and function of insulin-like growth factors and insulin-like growth factor-binding protein 3 in animal models of AD, as well as reduce insulin resistance in healthy older adults." (PMID 31788339, 2019). "Importantly, correction of insulin resistance, along with other related mechanisms, through the use of add-on insulin sensitizer therapy, has been demonstrated in clinical trials to improve antidepressant treatment response in patients with treatment-resistant depression." (PMID 30803432, 2019). "Thus, our findings suggest that SOCS-dependent regulation of insulin signaling may additionally modify the progress of insulin resistance in NAFLD patients." (PMID 31717271, 2019). "Therefore, targeting regulation of AMPK and insulin signaling pathway might be a new and useful therapeutic approach to drop lipid accumulation and insulin resistance in NAFLD." (PMID 31803542, 2019). "Our study suggests the relevance of better understanding these transcription factors in visceral adipose tissue to determine their possible role in the etiology of obesity-related insulin resistance in an insulin-independent manner, which could lead to new therapeutic and anti-diabetic strategies." (PMID 31547433, 2019).
Insulin resistance (continued). "As such, preventive modulation of the gut microbiota may need to target different bacteria in those with IGT compared with impaired fasting glucose as insulin resistance has been shown to be more predictive of IGT while impaired insulin secretion is more predictive of IFG." (PMID 30987356, 2019). "The primary hypothesis of our study was to determine if high dose RES, administered to obese men with insulin resistance and the MetS, would improve insulin sensitivity, glucose tolerance, and other features of the MetS and thus possibly contribute to established therapies of the disease." (PMID 30873501, 2019). "These may be associated with women diagnosed with GDM having high level insulin resistance and decreased insulin secretory capacity compared with non-GDM." (PMID 30388861, 2018). "When compared with a high-carbohydrate, low-fat diet that produced similar weight loss, a commonly used VLC diet failed to improve whole body insulin resistance; it also reduced insulin’s effect on hepatic gene expression, which may reflect the development of hepatic insulin resistance." (PMID 31061673, 2018). "We hypothesized that the combination of freeze-dried aronia, red ginseng, ultraviolet-irradiated shiitake mushroom and nattokinase would prevent or reverse insulin resistance, improve insulin secretion, and help normalize serum glucose levels, due to changes in the gut microbiome." (PMID 30041479, 2018). "A third potential mechanism that links dyslipidemia, glycemic control, and adiposity in type 1 diabetes is insulin resistance, a phenomenon that has been described in type 1 diabetes owing to the rising prevalence of obesity, sedentary lifestyle, and chronic exogenous insulin administration." (PMID 29768449, 2018). "Randomized controlled trials sustain also that the consumption of whole grains improves blood glucose control, may reduce fasting insulin levels, and reduces insulin resistance, indicating that a whole grain diet may increase insulin sensitivity, which controls blood sugar levels." (PMID 30388881, 2018). "The underlying hypothesis was that the metabolic traits of insulin resistance associated with prolonged fasting involves substrate competition, and not impaired insulin signaling." (PMID 30183740, 2018). "Moreover, hyperinsulinemia and insulin resistance may mediate cancer progression via the insulin/insulin-like growth factor axis." (PMID 29662006, 2018). "Besides the bone metabolism role, vitamin D also has the ability to reduce the level of RBP4 and to provide vascular protection, which is partly associated with inhibiting cholesterol biosynthesis, relieving inflammation reaction, improving insulin resistance, and increasing insulin sensitivity." (PMID 30186876, 2018). "The mechanism may be related to insulin resistance and insulin sensitivity." (PMID 29686322, 2018). "Moreover, serum BSP concentrations did not correlate with the patients’ body mass index (BMI) or markers for a deregulated metabolic state (serum levels of Adiponectin, Leptin, leptin receptor) or insulin resistance (serum levels of Insulin, C-peptide, HbA1c, HOMA)." (PMID 29950701, 2018). "Furthermore, decreasing insulin resistance after the intake of inositol may be due to an improvement in peripheral insulin sensitivity." (PMID 29793496, 2018). "In addition, HFD mice displayed elevated basal glucose (200.74 ± 8.9 mg/dl vs. 153.3 ± 4.73, N = 20/group – measured before initiation of the pharmacological intervention; p = 0.012) and insulin levels (p = 0.028), as evidence for a state of insulin resistance." (PMID 30382123, 2018). "Moreover, in contrast with most studies using the homeostasis model (HOMA-IR) as an indicator of insulin resistance, we used a fasting insulin assessment because it can be a more sensitive indicator of insulin resistance even in children without elevated glycaemia." (PMID 29360869, 2018).